TRAPPC13 (trafficking protein particle complex subunit 13)
Description:
Component of the multisubunit TRAPP (transport protein particle) III complex. As a component of TRAPPIII complex, participates in the activation of RAB1 and RAB43, but not RAB11A, RAB11B, nor RAB19.
Synonyms: C5orf44; FLJ13611; MGC48585
Tractability: Antibody: the Human Protein Atlas places it where antibodies can reach. PROTAC: ubiquitination databases record sites on it; its protein half-life has been measured.
Gene: Protein-coding gene on chromosome 5 (65,624,789 to 65,666,233, forward strand). Ensembl gene ENSG00000113597.
Subcellular location (Human Protein Atlas): Nucleoplasm; Plasma membrane
Pathways (Reactome):
Vesicle-mediated transport: RAB GEFs exchange GTP for GDP on RABs
Gene Ontology:
Molecular function: protein binding
Biological process: endoplasmic reticulum to Golgi vesicle-mediated transport; vesicle coating
Cellular component: cytoplasm; cytosol; TRAPPII protein complex; TRAPPIII protein complex
Genetic constraint (gnomAD): Loss-of-function variants: 25 observed, 31.5 expected, observed/expected ratio (o/e) 0.79, 90% interval 0.58 to 1.11. The upper end of that interval is the gene's LOEUF score, 1.11, which puts it in group 4 of 6, group 1 being the genes least tolerant of losing a copy. Missense variants: 310 observed, 375.04 expected, observed/expected ratio (o/e) 0.83, 90% interval 0.75 to 0.91. Synonymous variants: 123 observed, 133.51 expected, observed/expected ratio (o/e) 0.92, 90% interval 0.8 to 1.07.
Homologues: Orthologues: chimpanzee TRAPPC13 (100% identical), macaque TRAPPC13 (99% identical), rabbit TRAPPC13 (99% identical), dog TRAPPC13 (98% identical), rat Trappc13 (97% identical), mouse Trappc13 (97% identical), pig TRAPPC13 (93% identical), tropical clawed frog trappc13 (90% identical), guinea pig TRAPPC13 (89% identical), zebrafish trappc13 (86% identical), Drosophila melanogaster CG4953 (46% identical), Caenorhabditis elegans C56C10.7 (45% identical).
Diseases named in the same sentence as TRAPPC13 in open-access papers:
TRAPPC13 is named in the same sentence as 1 disease in open-access papers, as found by Europe PMC text mining. Sharing a sentence is not in itself a finding about the gene and the disease. The quoted sentences say what the papers report.
endometritis (2 papers, 2023). An acute or chronic, usually bacterial infectious process affecting the endometrium. "Specific mRNA expression patterns of C3, C2, LTF, PF4, and TRAPPC13 are present in the blood and endometrium of dairy calves with subclinical endometritis." (PMID 37756095, 2023). "Additionally, C3, C2, LTF, PF4, and TRAPPC13 had unique mRNA expression patterns in the blood and endometrial tissue of dairy cows with subclinical endometritis." (PMID 37368756, 2023). "Additionally, in contrast to cows with sub-clinical endometritis, the gene expression profiles of C3, CXCL8, LTF, TLR2, and TRAPPC13 were temporally changed in healthy cows’ circulating WBC during the postpartum period." (PMID 37756095, 2023).